COL18A1 (collagen type XVIII alpha 1 chain)
Description:
Probably plays a major role in determining the retinal structure as well as in the closure of the neural tube. [Non-collagenous domain 1]: May regulate extracellular matrix-dependent motility and morphogenesis of endothelial and non-endothelial cells; the function requires homotrimerization and implicates MAPK signaling. [Endostatin]: Potently inhibits endothelial cell proliferation and angiogenesis. May inhibit angiogenesis by binding to the heparan sulfate proteoglycans involved in growth factor signaling (By similarity). Inhibits VEGFA-induced endothelial cell proliferation and migration. Seems to inhibit VEGFA-mediated signaling by blocking the interaction of VEGFA to its receptor KDR/VEGFR2. Modulates endothelial cell migration in an integrin-dependent manner implicating integrin ITGA5:ITGB1 and to a lesser extent ITGAV:ITGB3 and ITGAV:ITGB5 (By similarity). May negatively regulate the activity of homotrimeric non-collagenous domain 1.
Synonyms: KS; KNO1; GLCC; KNO
Tractability: Antibody: UniProt places it where antibodies can reach, with high confidence; its Gene Ontology location is reachable by antibodies, with high confidence; UniProt predicts a signal peptide or a membrane-spanning region. PROTAC: ubiquitination databases record sites on it; its protein half-life has been measured. Other modalities: an approved drug acts on it.
Gene: Protein-coding gene on chromosome 21 (45,405,123 to 45,513,721, forward strand). Ensembl gene ENSG00000182871.
Subcellular location: Secreted, extracellular space, extracellular matrix; Secreted, extracellular space, extracellular matrix, basement membrane; Secreted, extracellular space, extracellular matrix, basement membrane (Non-collagenous domain 1); Secreted; Secreted (Endostatin)
Subcellular location (Human Protein Atlas): Golgi apparatus; Predicted to be secreted
Pathways (Reactome):
Extracellular matrix organization: Activation of Matrix Metalloproteinases; Assembly of collagen fibrils and other multimeric structures; Collagen biosynthesis and modifying enzymes; Collagen chain trimerization; Collagen degradation; Integrin cell surface interactions; Laminin interactions
Gene Ontology:
Molecular function: extracellular matrix structural constituent conferring tensile strength
Biological process: angiogenesis; animal organ morphogenesis; endothelial cell morphogenesis; extracellular matrix organization; negative regulation of cell population proliferation; skeletal system development; visual perception; anatomical structure morphogenesis; regulation of cell population proliferation; response to hydrostatic pressure; response to xenobiotic stimulus
Cellular component: extracellular exosome; extracellular matrix; extracellular region; collagen trimer; collagen type XVIII trimer; elastic fiber; endoplasmic reticulum lumen; basement membrane
Genetic constraint (gnomAD): Loss-of-function variants: 113 observed, 132 expected, observed/expected ratio (o/e) 0.86, 90% interval 0.73 to 1. The synonymous counts are far from expectation, so gnomAD's model fits this gene poorly and the ratio says little. Missense variants: 1,920 observed, 1,609.3 expected, observed/expected ratio (o/e) 1.19, 90% interval 1.15 to 1.24. Synonymous variants: 860 observed, 670.55 expected, observed/expected ratio (o/e) 1.28, 90% interval 1.21 to 1.36.
Gene-disease validity (ClinGen):
ClinGen rates the evidence that COL18A1 causes each of these diseases.
Knobloch syndrome 1 (autosomal recessive): Definitive.
Homologues: Orthologues: chimpanzee COL18A1 (97% identical), macaque COL18A1 (93% identical), dog COL18A1 (78% identical), pig COL18A1 (78% identical), rat Col18a1 (77% identical), mouse Col18a1 (77% identical), guinea pig COL18A1 (65% identical), tropical clawed frog col18a1 (56% identical), zebrafish col18a1a (48% identical), zebrafish col18a1b (31% identical). Paralogues in human: COL4A5 (27% identical), COL17A1 (26% identical), COL5A1 (26% identical), COL11A1 (26% identical), COL4A1 (26% identical), COL4A4 (26% identical), COL2A1 (25% identical), COL1A1 (25% identical), COL4A3 (25% identical), COL4A2 (25% identical), COL5A2 (25% identical), COL5A3 (25% identical), and 25 more.
Diseases named in the same sentence as COL18A1 in open-access papers:
COL18A1 is named in the same sentence as 142 diseases in open-access papers, as found by Europe PMC text mining. Sharing a sentence is not in itself a finding about the gene and the disease. The quoted sentences say what the papers report.
Knobloch syndrome (28 papers, 2007 to 2026). "Initial mild homocysteine elevation prompted consideration of homocystinuria; however, whole-exome sequencing identified a homozygous frameshift mutation in COL18A1 (c.2824_2831del, p.Gly942Argfs*142), confirming Knobloch syndrome type 1." (PMID 41767075, 2026). "Knobloch syndrome (KNO) is an autosomal recessive disorder caused by mutations in the COL18A1 gene, which plays a critical role in ocular embryogenesis." (PMID 40428839, 2025). "There are two types of Knobloch syndrome: Type 1, caused by mutations in the COL18A1 gene, which disrupts collagen production, a key structural protein; and Type 2, linked to mutations in the PAK2 gene, which regulates cell growth and signaling." (PMID 40262506, 2025). "Biallelic variants in the COL18A1 gene were first described to cause a very rare autosomal recessive syndrome known as Knobloch syndrome (KS), characterized by a range of ocular, genitourinary and CNS defects." (PMID 38783254, 2024). "COL18a1 is mostly expressed in the brain and eye, and associated with the Knobloch syndrome, which leads to eye deformations in the development phase, called occipital encephalocele." (PMID 38997817, 2024). "We described three families with Knobloch Syndrome 1 who share the same recurrent variant in the COL18A1 gene." (PMID 39457419, 2024). "The predominant molecular pathogenic mechanism associated with Knobloch Syndrome 1 (KS) is loss-of-function mutations in the COL18A1 gene." (PMID 39457419, 2024). "Variants in COL18A1 have been identified in patients with Knobloch syndrome, an inherited disorder characterized by HM, retinal detachment, and occipital defects." (PMID 38039006, 2023). "Knobloch syndrome is an autosomal recessive disorder associated with pathogenic variants of the COL18A1 gene encoding the α1 chain of type 18 collagen." (PMID 35741851, 2022). "High myopia with alopecia areata in the occipital region has been observed in patients with Knobloch syndrome caused by COL18A1 mutations." (PMID 34249907, 2021). "Further assessments indicated that patients with COL18A1 mutations had Knobloch syndrome, and the patients with LAMA1 mutations had Poretti–Boltshauser syndrome." (PMID 34249907, 2021). "We reported six patients with Knobloch syndrome from four unrelated families in whom we identified five novel COL18A1 mutations." (PMID 34680907, 2021). "A previously undiagnosed patient was found to be homozygous for the COL18A1 pathogenic variant, c.3523_3524delCT; p.(Leu1175ValfsTer72), associated with Knobloch syndrome." (PMID 34828430, 2021). "This study aimed to investigate novel variants of COL18A1 in Knobloch syndrome and describe the associated phenotypes in Chinese patients." (PMID 34680907, 2021). "COL18A1, however, has been associated with Knobloch syndrome, which itself is characterized by severe vision problems including high myopia and retinal detachment." (PMID 33396423, 2020). "COL18A1 mutations, the vast majority of which are nonsense mutations, cause recessive Knobloch syndrome (OMIM # 267750) that is characterised by eye defects (e.g. myopia, vitreoretinal degeneration, macular abnormalities) and occipital encephalocele." (PMID 31387942, 2019). "Deficiency of Col18a1 in mice mimics Knobloch syndrome but also affects the kidney and fat metabolism." (PMID 31387942, 2019). "The other variant affects the COL18A1 gene, which is known to cause the Knobloch syndrome (severe vision impairments with occipital encephalocele), both features lacking in our patient." (PMID 29946244, 2018). "Intriguingly, mutations in human collagen XVIII (COL18A1) are associated with Knobloch syndrome, a rare autosomal recessive disorder characterized by severe vision problems including vitreoretinal degeneration." (PMID 27261002, 2016). "There is no reported information on cardiac specific mutations linked with COL18A1 in humans, however the gene is linked with Knobloch syndrome-1." (PMID 26815362, 2016).
Knobloch syndrome (continued). "A combination of homozygosity mapping and whole exome sequencing (WES) identified a novel mutation in COL18A1 and led to the diagnosis of Knobloch syndrome." (PMID 25392994, 2014). "Identification of a mutation in COL18A1 led to a retrospective clinical analysis upon which the clinical diagnosis was confirmed to be Knobloch syndrome." (PMID 25392994, 2014). "Since we found a mutation in COL18A1, a gene that had been previously associated with Knobloch syndrome, we reanalyzed the clinical data in depth." (PMID 25392994, 2014). "COL18A1 mutations involved in Knobloch syndrome have a distribution bias toward the coding exons of the C-terminal end." (PMID 19390655, 2009). "The candidates in this study were used in previous investigations of single gene disorders predisposed to myopia (COL2A1 and Stickler Syndrome, COL18A1 and Knobloch Syndrome)." (PMID 17653045, 2007). "Knobloch syndrome is associated with mutations in the COL18A1 gene on chromosome 21." (PMID 38575892, 2024). "There may be also some overlap between PDS and the rare recessive disease Knobloch syndrome (OMIM number 267750) caused by mutations in COL18A1." (PMID 29780638, 2018). "Mutations in COL18A1 are known to cause Knobloch syndrome (KS)." (PMID 25392994, 2014). "In humans, loss of function mutations in COL18A1 cause Knobloch syndrome (OMIM 267750)." (PMID 21085708, 2010). "Knobloch syndrome is a rare collagenopathy characterized by severe early onset myopia, retinal detachment, and occipital encephalocele with various additional manifestations due to biallelic changes in the COL18A1 gene." (PMID 35693012, 2022). "Mutations in COL18A1 are specific to Knobloch Syndrome and no additional gene has been identified so far." (PMID 25392994, 2014). "Knobloch syndrome is an autosomal recessive disease characterized by high myopia, vitreoretinal degeneration and occipital encephalocele, and is caused by mutations in the collagen, type XVIII, alpha 1 (COL18A1) locus." (PMID 21527992, 2011). "To facilitate future diagnosis of Knobloch syndrome (KS) and better understand its etiology, we sought to identify not yet described COL18A1 mutations in KS patients." (PMID 19390655, 2009). "However, given the severity of the other diagnostic symptoms of Knobloch syndrome, variants in COL18A1 are unlikely to cause a large proportion of PDS/PG cases." (PMID 29780638, 2018).
myopia (9 papers, 2007 to 2025). "High myopia, defects in the occipital region, and COL18A1 mutation supported a diagnosis of KNO for all three patients." (PMID 34249907, 2021). "Similarly to COL2A1, biallelic pathogenic variants in COL18A1 are consistently associated with high myopia as shown across cohort and case studies." (PMID 41153400, 2025). "Physical examination of the skin of the scalp could be a fast and convenient way for ophthalmologists to detect signs for considering KNO and COL18A1 mutations when treating children with high myopia." (PMID 34249907, 2021). "Our study found that early onset high myopia with midline alopecia areata could be caused not only by mutations of the COL18A1 gene but also by mutations in the LAMA1 gene." (PMID 34249907, 2021). "SNPs were also analyzed in genes where their expression pattern or their association with syndromes conveys myopia as part of the phenotype (FGF2, BDNF, COL2A1, COL18A1, and PAX6)." (PMID 17653045, 2007). "In summary, we examined using a DNA pooling approach tag SNPs from four candidate genes (COL11A1, COL18A1, FBN1, and PLOD1) selected because pathogenic mutations in these genes cause disease syndromes that have myopia, usually high myopia, as one of the common presenting clinical features." (PMID 21527992, 2011). "Two of the aunts (III-10 and III-11) also showed high myopia but this condition did not cosegregate with the identified COL18A1 frameshift deletion." (PMID 25392994, 2014). "In conclusion, common polymorphisms in these four candidate genes (COL11A1, COL18A1, FBN1, and PLOD1) were unlikely to play important roles in the genetic susceptibility to high myopia." (PMID 21527992, 2011).
breast carcinoma (8 papers, 2012 to 2025). "A study found that the risk of sporadic breast cancer was significantly increased in patients with the COL18A1 D104N polymorphism." (PMID 35149954, 2022). "This is reflected in our 18-gene signature, with three of five RNAs upregulated in PAFs and for which higher expression in breast cancers was associated with poor prognosis encoded collagen proteins (Col5a2, Col13a1, Col18a1)." (PMID 34565423, 2021). "Studies have reported that SNPs in COL18A1 are associated with numerous cancers, such as breast cancer, prostate carcinoma, colorectal adenocarcinoma and lung cancer." (PMID 22461898, 2012). "In this study, we performed RNA-sequencing for ER-positive breast cancer cells and identified a novel estrogen-inducible antisense RNA in the COL18A1 promoter region, named breast cancer natural antisense transcript 1 (BNAT1)." (PMID 36429038, 2022). "TNC, COL18A1 and COL12A1 gene expression characterize fibroblasts known as ECM-CAF (Extracellular Matrix-Cancer Associated Fibroblasts) which participates in the aberrant remodeling of the extracellular matrix in breast cancer." (PMID 39239354, 2024). "Others, such as COL18A1, TGFBI, FGB, ITIH2, ITIH4, and TNC among others, were overrepresented in 3 of 4 signatures and also expressed in mammary carcinoma xenografts." (PMID 37098922, 2023).
glioma (6 papers, 2015 to 2024). A benign or malignant brain and spinal cord tumor that arises from glial cells (astrocytes, oligodendrocytes, ependymal cells). "In glioma, upregulated miR‐9 inhibits the expression of COL18A1, THBS2, PTCH1 and PHD3, promoting tumorigenesis and angiogenesis." (PMID 39648148, 2024). "miR-9 promotes the angiogenesis and tumorigenesis of glioma by targeting COL18A1, THBS2, PTCH1 and PHD3 directly." (PMID 32958011, 2020). "Our study firstly established a seven-gene signature comprising METTL3, COL18A1, NASP, PHLPP2, TIMP1, U2AF2, and VEGFA with a good capability for predicting survival in glioma." (PMID 34589481, 2021). "Our study established and validated a seven-gene signature comprising METTL3, COL18A1, NASP, PHLPP2, TIMP1, U2AF2, and VEGFA, with a good capability for predicting glioma survival, which may guide therapeutic customization and clinical decision-making." (PMID 34589481, 2021). "Collectively, m6A RNA methylation regulators KIAA1429, METTL16, METTL3, IGF2BP2, and YTHDF, and targets NASP, TIMP1, U2AF2, COL18A1, and VEGFA could serve as oncogenes in glioma, while PHLPP2 is a tumor suppressor." (PMID 34589481, 2021). "Endogenous levels of these targets displayed a significantly negative correlation with miR-9 expression in glioma cells, strongly indicating an inverse relationship between miR-9 and COL18A1, THBS2, PTCH1 and PHD3." (PMID 30795814, 2019). "In addition to COL18A1, THBS2 is involved in the focal adhesion pathway in human SNB19 glioma cells and functions as an endogenous inhibitor of angiogenesis." (PMID 30795814, 2019). "COL18A1, THBS2, PTCH1 and PHD3 were verified as the direct targets of miR-9, which could elucidate the miR-9-induced malignant phenotypes in glioma cells." (PMID 30795814, 2019). "In our study, we confirm that miR-9 can directly bind to the 3’-UTR of COL18A1, THBS2, PTCH1 and PHD3, promote the degradation of these mRNAs and initiate HIF-1α/VEGF signal transduction, thus markedly enhancing tumorigenesis and angiogenesis during the glioma progression." (PMID 30795814, 2019).
glaucoma (4 papers, 2018 to 2025). Increased pressure in the eyeball due to obstruction of the outflow of aqueous humor. "Notably, emerging molecular epidemiology evidence demonstrates that polymorphic variants in COL15A1 and COL18A1 genes substantially modulate the temporal onset and clinical trajectory of primary open-angle glaucoma (POAG)." (PMID 40176796, 2025). "In this category, the Col18a1 gene caught our attention since (i) it is a direct YAP target gene, (ii) it is essential for retinal angiogenesis, and (iii) it is recognized as a genetic risk factor in one glaucoma type, namely pigmentary glaucoma." (PMID 38272861, 2024). "However, the involvement of SLC4A11 and COL18A1 with glaucoma cases has been reported in the literature." (PMID 38755526, 2024). "All variants detected were in genes previously associated with glaucoma and are “Green” in the glaucoma panel of PanelApp except SLC4A11 and COL18A1 which are not in the glaucoma panel, but are rated “Green” in the corneal abnormalities (v1.12) and structural eye disease (v3.2) panels, respectively." (PMID 38755526, 2024).
ovarian carcinoma (4 papers, 2019 to 2023). A malignant neoplasm originating from the surface ovarian epithelium. "It is also noticed that the origins of high COL1A1, COL1A2, and COL3A1 expression positively correlate with fibroblast-specific markers (FAP) and smooth muscle actin (ACTA2), whereas COL4A1, COL4A2, and COL18A1 seem to be predominantly expressed in ovarian cancer cells." (PMID 33026975, 2020). "In addition, COL18A1 has been proved to be a promising biomarker for ovarian cancer and was possibly involved in the progression of bladder cancer." (PMID 31598423, 2019). "COL18A1 and B4GALNT4 are also overexpressed in endometrial and ovarian cancers according to the HPA and are unfavorable markers for overall survival for both cancers." (PMID 37775701, 2023).
retinal detachment (4 papers, 2020 to 2024). An eye emergency condition which may lead to blindness if left untreated. "RPCs increased the expression of Col8a1, Col14a1, Col16a1 and Col18a1, among them, Col18a1 has been reported to be associated with macular edema, neovascularization, and retinal detachment in DR26." (PMID 37670124, 2023).
Ataxia (3 papers, 2016 to 2024). Ataxia refers to impaired coordination of voluntary muscle movement. "In addition, a mutation in COL18A1 has been identified in an Indian family with SCA7-like symptoms including ataxia and progressive blindness." (PMID 27261002, 2016). "Thus, we speculate that downregulation of COL18A1 expression in glia in SCA7 patients could contribute to the specific visual degeneration associated with this ataxia." (PMID 27261002, 2016). "Pathogenic variants in COL18A1, UFSP2, ZFYVE26, and ATP13A2 contribute to a wide range of clinical phenotypes, from ASM-resistant epilepsy and developmental delay to ataxia, intellectual disability, speech impediment, and other associated symptoms." (PMID 38783254, 2024). "Mutations in the human ortholog of Mp, COL18A1, have been identified in a family with a SCA7-like progressive visual disorder, suggesting that defects in the expression of this gene in SCA7 patients could play a role in the retinal degeneration that is unique to this ataxia." (PMID 27261002, 2016).
atopic dermatitis (3 papers, 2009 to 2023). "Proinflammatory FB populations have been recently described in other inflammatory skin diseases, including Th2 responsive COL6A5+COL18A1+ FBs in atopic dermatitis and T cell–attracting CXCL9/CXCL10-expressing FBs in vitiligo." (PMID 37471168, 2023). "In addition, the SFRP2+ inflammatory fibroblasts in psoriasis share with the COL6A5+COL18A1+ fibroblasts in atopic dermatitis the expression of CCL19 which is capable of recruiting CCR7+LAMP3+ cDC2A61." (PMID 37308489, 2023). "A non-synonymous SNP in COL18A1, intronic variants in MAP3K5 and a polymorphism in COL29A1, previously related to atopic dermatitis, were also associated with atopy, but not consistently replicated." (PMID 19961619, 2009).